MAT2A (methionine adenosyltransferase 2A)
Diseases named in the same sentence as MAT2A in open-access papers (continued):
Sharing a sentence is not in itself a finding about the gene and the disease.
leukemia (5 papers, 2020 to 2025). A malignant (clonal) hematologic disorder, involving hematopoietic stem cells and characterized by the presence of primitive or atypical myeloid or lymphoid cells in the bone marrow and the blood. "However, in leukemia, the pathogenic function of MAT2A was only defined within specific leukemia subtypes, such as T- acute lymphoblastic leukemia (ALL)." (PMID 32456310, 2020). "We thereby establish the preclinical rationale to target MAT2A in leukemia patients harboring MLL translocations." (PMID 32456310, 2020). "Taken together, our data show that MAT2A is required for the survival advantage and the myeloid differentiation block as characteristics of MLLr leukemia." (PMID 32456310, 2020). "In MLLr leukemia, the MAT2A product SAM serves as a substrate for many important methyltransferases like the H3K79 histone methyltransferase DOT1L or PRMT5, both involved in the pathogenesis of the disease." (PMID 32456310, 2020). "In this study, we demonstrated an MAT2A dependency in MLLr leukemogenesis, constituting an ideal target in the treatment of poor prognosis MLLr leukemia." (PMID 32456310, 2020). "We analyzed both publicly available datasets and our own data and retrieved MAT2A as a major player in MLLr leukemogenesis, showing the highest expression level within this specific leukemia subtype." (PMID 32456310, 2020). "MAT2A is known to be overexpressed in many cancer types, particularly in leukemias." (PMID 38643304, 2024). "Taken together, our results provide a proof-of-principle and preclinical evidence that MAT2A inhibition leads to anti-leukemic effects in MLLr leukemia and can easily be combined with other targeted therapies or chemotherapy to overcome the poor prognosis in MLLr leukemia." (PMID 32456310, 2020). "Here, we used our human CRISPR/Cas9-MLL-rearranged (CRISPR/Cas9-MLLr) leukemia model, faithfully mimicking MLLr patients’ pathology with indefinite growth potential in vitro, to evaluate the unknown role of MAT2A." (PMID 32456310, 2020). "In line with our study, this observation further supports the relevance of MAT2A in MLLr leukemia." (PMID 32456310, 2020). "Methionine metabolism: Through the SETD2-dependent histone H3K36 methylation pathway, methionine adenosyltransferase 2A (MAT2A) promotes the conversion of methionine to S-adenosylmethionine (SAM), which preserves leukemia-specific epigenetic characteristics." (PMID 41451233, 2025). "In addition, MAT2A has been identified as a critical enzyme in CSCs, MLL-r leukemias, and cancers that lack methylthioadenosine-phosphorylase (MTAP), which accounts for 15% of all cancers." (PMID 38643304, 2024). "Recently, the MAT2A inhibitor PF-9366 with high affinity has been described to efficiently block SAM synthesis, allowing for the first time an evaluation of MAT2A as a therapeutic target in MLLr leukemia." (PMID 32456310, 2020). "In primary patient leukemia, MLLr leukemia showed the highest MAT2A expression compared to non-MLLr leukemia and healthy controls, respectively." (PMID 32456310, 2020). "For the first time, by using the novel allosteric MAT2A inhibitor PF-9366, we were able to uncover MAT2A as both a key regulator in MLL leukemogenesis and as new therapeutic target in the treatment of poor prognosis MLLr leukemia." (PMID 32456310, 2020). "Here, we show that MAT2A is aberrantly overexpressed in MLLr leukemia compared to non-MLLr leukemia and healthy controls." (PMID 32456310, 2020).
liver cirrhosis (4 papers, 2008 to 2022). "SAM is synthesized from methionine by the enzyme methionine adenosyltransferase, which is encoded by the genes MAT1A and MAT2A (Mat1a and Mat2a in mice); patients with liver cirrhosis have a 50%-reduced activity of this enzyme." (PMID 29285212, 2017). "Liver cirrhosis and HCC of rodents and humans are characterized by a decrease of MAT1A expression and a rise in MAT2A expression with a consequent decrease of MAT1A:MAT2A ratio (the so-called MAT1A/MAT2A switch)." (PMID 35159219, 2022).
lung adenocarcinoma (4 papers, 2013 to 2024). A carcinoma that arises from the lung and is characterized by the presence of malignant glandular epithelial cells. "In addition, the study demonstrated the overexpression and tumor-promoting potential of two key methionine regulators (Methionine adenosyltransferase 2A [MAT2A] and Methylenetetrahydrofolate Reductase [MTHFR]) in lung adenocarcinoma." (PMID 37179124, 2023). "CDK13, BMP1, RNF13, MAT2A, CHRNA4 are also among the genes in Merged-module whose over-expression has been reported in different cancers, however, their over-expression has been demonstrated in lung adenocarcinoma in this study." (PMID 23874428, 2013).
lung cancer (4 papers, 2020 to 2023). A malignant neoplasm involving the lung. "MAT2A reversed the effects of miR-136 on lung cancer cell growth, invasion, and cancer stem cell characteristics." (PMID 34258296, 2021). "In summary, our study revealed that the circ_0044516/miR-136/MAT2A axis is involved in lung cancer progression." (PMID 34258296, 2021). "Nevertheless, the effects of MAT2A on lung cancer progression remains poorly understood." (PMID 34258296, 2021). "We reported that circ_0044516 might sponge miR-136 to regulate MAT2A expression, leading to lung cancer progression." (PMID 34258296, 2021). "In summary, these results demonstrated that circ_0044516 could function as a sponge for miR-136 to promote lung cancer progression by inducing MAT2A expression." (PMID 34258296, 2021). "MAT2A was predicted and confirmed as a target of miR-136 in lung cancer." (PMID 34258296, 2021). "Furthermore, we reported that circ_0044516 contributes to lung cancer by modulating miR-136 and MAT2A, which indicated that the circ_0044516/miR-136/MAT2A axis could be a crucial therapeutic target in lung cancer." (PMID 34258296, 2021). "A recent study has revealed a tumor-initiating capability of methionine cycle activity and two methionine regulators (MAT2A and MTHFR) in lung cancer." (PMID 37179124, 2023).
Cirrhosis (3 papers, 2008 to 2022). A chronic disorder of the liver in which liver tissue becomes scarred and is partially replaced by regenerative nodules and fibrotic tissue resulting in loss of liver function. "MAT1A gene is specifically silenced by hypermethylation in human cirrhosis, which leads to a marked reduction of SAMe synthesis, We discovered the SAMe content could be decreased by knocking down MAT2A and increased by knocking down MAT2β which were in agreement with the results of Komal." (PMID 19025580, 2008). "Chronic hepatitis and cirrhosis and HCC of rodents and humans are characterized by a fall in MAT1A expression and a rise in MAT2A expression, with consequent decrease of MAT1A: MAT2A ratio (an event referred to as “MAT1A/MAT2A switch”)." (PMID 31569678, 2019).
colorectal cancer (3 papers, 2021 to 2024). A primary or metastatic malignant neoplasm that affects the colon or rectum. "MAT2a inhibitors are now in clinical trials for genotypic MTAP−/− cancers, however the MTAP−/− genotype represents fewer than 2% of human colorectal cancers (CRCs), limiting the utility of MAT2a inhibitors in these and other MTAP+/+ cancers." (PMID 38000655, 2024). "Challenges for the use of MAT2a inhibitors include the variable frequency of the MTAP−/− genotype, which ranges from 55% prevalence in glioblastoma to 2% in colorectal carcinoma, limiting the broader application of these therapeutics." (PMID 38000655, 2024). "The expression of MAT2A and MAT2B is induced in HCC and colorectal cancers (CRC)." (PMID 34209866, 2021).
melanoma (3 papers, 2023 to 2025). A malignant, usually aggressive tumor composed of atypical, neoplastic melanocytes. "Methionine dependence in melanoma is influenced by the expression and activity of enzymes involved in methionine metabolism, such as methionine adenosyltransferase 2 alpha (MAT2A), which synthesizes s-adenosylmethionine (SAM) from methionine." (PMID 39766809, 2024).
osteosarcoma (3 papers, 2021 to 2025). A usually aggressive malignant bone-forming mesenchymal neoplasm, predominantly affecting adolescents and young adults. "RBM15 suppressed the ferroptosis and promoted proliferation and metastasis in osteosarcoma cells by mediating the m6A modification of MAT2A." (PMID 40682199, 2025). "Previous studies have shown that miR-26b-5p targets methionine adenosyltransferase 2A (MAT2A), leading to reduced GSH levels and promoting ferroptosis by blocking the STAT3/SLC7A11 pathway in osteosarcoma." (PMID 40403492, 2025).
pancreatic cancer (3 papers, 2017 to 2025). "Indeed, both SAMe and MTA treatment lowered the expression of MAT2A and MAT2B, which increased migration of prostate and pancreatic cancer cells when overexpressed." (PMID 29108270, 2017).
renal cell carcinoma (3 papers, 2014 to 2021). "But the relationship of MAT2A between renal cell carcinomas (RCC) is less understood." (PMID 24636201, 2014). "On the other hand, MAT2A expression was lower in the tumor tissues of human renal cell carcinomas (RCC), suggesting that MAT2A may have a potential role in the development of RCC." (PMID 34065390, 2021).
Aortic dissection (2 papers, 2022). Aortic dissection refers to a tear in the intimal layer of the aorta causing a separation between the intima and the medial layers of the aorta. "WES identified recurrent gain-of-function mutations in PRKG1 as causative for thoracic aortic aneurysms and acute aortic dissections, meanwhile MAT2A, LOX, and FOXE3 have been suggested as predisposing genes." (PMID 35892496, 2022). "Methionine adenosyltransferase 2A (MAT2A), another aortic dissection risk-associated gene, has previously been suggested to be a VSMC metabolism gene, however, recent work in hepatic stellate cells has also identified MAT2A as a downstream target of TGF-β." (PMID 36561772, 2022).
atherosclerosis (2 papers, 2023 to 2025). A disease characterized by the build-up of fatty material and calcium deposition in the arterial wall resulting in partial or complete occlusion of the arterial lumen. "Six shared loci that were shared across all traits in the analysis, all with known associations with atherosclerosis (nearest genes: MAT2A, IRS1, STAG1, PVRL2, OPRL1, ARVCF)." (PMID 40313769, 2025). "We used the endothelial marker gene CDH5 to identify a cluster of endothelial cells and confirmed that these cells express DHX38, MAT2A, CCDC92, FES and FURIN, prompting future efforts to dissect the role of these genes in this cell type in atherosclerosis." (PMID 36928188, 2023).
cholangiocarcinoma (2 papers, 2022 to 2023). A carcinoma that arises from the intrahepatic biliary tree (intrahepatic cholangiocarcinoma) or from the junction, or adjacent to the junction, of the right and left hepatic ducts (hilar cholangiocarcinoma). "Just as we had expected, inhibition of MAT2A greatly impaired 4-key-genes-mediated enhancement of stemness in cholangiocarcinoma cells." (PMID 35841118, 2022). "MAT2A was upregulated in cholangiocarcinoma (CHOL), colon adenocarcinomas (COAD), glioblastoma (GBM), head and neck squamous cell carcinoma (HNSC) with human papillomavirus (HPV) infection, LIHC, pheochromocytoma and paraganglioma (PCPG), and stomach adenocarcinoma (STAD), which were marked in red." (PMID 37240447, 2023). "Moderate to high expression of MAT2A and SP1 were present and co-localized in the nuclei in the cancerous tissue from an ESRRG-negative cholangiocarcinoma patient." (PMID 37240447, 2023). "In our study, we demonstrated that CSCs in cholangiocarcinoma have different methionine metabolic features, and 4-key-genes (SDHAF2, MRPS34, MRPL11 and COX8A) could promote ICC stemness in a MAT2A-dependent manner." (PMID 35841118, 2022).
experimental autoimmune encephalomyelitis (2 papers, 2024). An autoimmune demyelinating disease of the central nervous system that is produced experimentally in animals by the injection of homogenized brain or spinal cord in Freund's adjuvant. "Some astrocytes are characterized by reduced gene expression driven by NRF2 and increased signaling of MAFG and MAT2a, promoting central system inflammation in experimental autoimmune encephalomyelitis, which may lead to the pathogenesis of MS." (PMID 39440247, 2024). "Since SAM is the principal donor of the methyl group in multiple physiological processes, MAT1A and MAT2A may participate in various inflammatory diseases, such as experimental autoimmune encephalomyelitis, alcoholic hepatitis, non-alcoholic fatty liver diseases, and inflammatory bowel diseases." (PMID 38130504, 2024).
glioblastoma (2 papers, 2022 to 2023). The most malignant astrocytic tumor (WHO grade IV). "Besides this, circ_0000337 upmodulates methionine adenosyltransferase 2A (MAT2A) expression, thus accelerating migration and invasion in glioblastoma cells." (PMID 35055115, 2022).
hepatic disease (2 papers, 2016 to 2025). "A shift from MAT1A to MAT2A/MAT2B is observed in multiple liver diseases, indicating its involvement in liver growth and dedifferentiation." (PMID 40034261, 2025). "The results obtained to date using models of hepatic disease show that altered concentrations of this metabolite commonly derive from the Mat1a/Mat2a expression switch, and post-translational modifications on cytosolic MATα1 induced by nitrosative and oxidative stress." (PMID 27548429, 2016).
Hepatic fibrosis (2 papers, 2021 to 2025). The presence of excessive fibrous connective tissue in the liver. "Carbon tetrachloride-induced MAT2A overexpression facilitates mouse hepatic fibrosis through the regulation of intracellular SAM concentration." (PMID 34065390, 2021).
immuno- deficiency (2 papers, 2023 to 2025). "Since MAT2A-mediated methionine metabolism is critical for the cisplatin resistance phenotype of BCa cells, the inhibition of MAT2A by circARHGAP10 over-expression and the restriction of methionine uptake were sufficient to overcome cisplatin resistance in vivo in an immuno- deficiency model." (PMID 41169378, 2025). "We further validated that knockdown of MAT2A through overexpression of circARHGAP10 and restriction of methionine up-take was sufficient to overcome cisplatin resistance in vivo in immuno-deficiency model but not in immuno- competent model." (PMID 37582769, 2023). "Knockdown of MAT2A through overexpression of circARHGAP10 and restriction of methionine up-take was sufficient to overcome cisplatin resistance in vivo in immuno-deficiency model but not in immuno-competent model." (PMID 37582769, 2023).
Insulin resistance (2 papers, 2022 to 2023). Increased resistance towards insulin, that is, diminished effectiveness of insulin in reducing blood glucose levels. "In addition, upregulation of MAT2A induced insulin resistance, possibly implicating methionine usage to the development of type II diabetes with aging." (PMID 36797255, 2023). "Notably, ammonium levels, insulin sensitivity, and glucose uptake were restored by knocking down or inhibiting MAT2A, suggesting that increased use of methionine might be contributing to insulin resistance." (PMID 36797255, 2023). "Furthermore, glucose and insulin tolerance tests (GTT and ITT, respectively) revealed that Mat2a deletion protected against HFD-induced glucose intolerance and insulin resistance." (PMID 35729157, 2022).
non-alcoholic fatty liver disease (2 papers, 2022 to 2024). "Non-alcoholic steatohepatitis (NASH) is the most severe form of non-alcoholic fatty liver disease (NAFLD) and supposed as a potential precursor of HCC.28 16 weeks after HFD feeding, fasting serum glucose and insulin levels were significantly decreased in Mat2a LKO mice." (PMID 35729157, 2022).
prostate carcinoma (2 papers, 2017 to 2023). A carcinoma that arises from epithelial cells of the prostate gland. "However, the subsequent investigation of the MAT2A inhibitor, the enzyme responsible for the conversion of L-methionine to SAM, only identified a susceptibility in prostate cancer cells maintained under chronic hypoxia." (PMID 37020039, 2023). "Like CRC, MAT2A and MAT2B expression is induced in human pancreas and prostate cancers." (PMID 29108270, 2017).
thyroid cancer (2 papers, 2023). "On the other hand, MAT2A was found to be downregulated in different tumor types, including bladder urothelial carcinoma (BLCA), kidney chromophobe (KICH), kidney renal papillary cell carcinoma (KIRP), and thyroid carcinoma (THCA), which were marked in blue." (PMID 37240447, 2023).
bladder cancer (1 paper, 2023). "However, among these metabolism pathways, only key enzymes in methionine metabolism as MAT2A was up-regulated in T24-CR cells according to proteomics data, which indicates methionine metabolism was crucial to cisplatin resistance in bladder cancer." (PMID 37582769, 2023).
breast tumor (1 paper, 2021). "A distinctly different expression pattern of MAT2A was observed between the breast tumor and normal samples: when compared to the normal breast tissues, the median of MAT2A mRNA expression level in breast tumorous tissues tended to be lower." (PMID 34065390, 2021). "We examined the specimens from 252 independent patients and compared the subcellular protein expression of GNMT, MAT1A, and MAT2A between the breast tumor and their paired normal breast tissues by Immunohistochemistry (IHC) analysis." (PMID 34065390, 2021).
colorectal tumors (1 paper, 2024). "As the majority of human tumors are MTAP+/+, including approximately 98% of colorectal tumors, MTDIA can be an effective strategy for sensitizing them to MAT2a inhibitors." (PMID 38000655, 2024).
diffuse midline glioma (1 paper, 2023). A diffuse glioma that arises from the midline structures of the central nervous system. "Pediatric diffuse midline gliomas with an H3K27M mutation have lower levels of methionine adenosyltransferase 2A (MAT2A) protein; depletion of residual MAT2A reduces global H3K4me3." (PMID 37444539, 2023).
disc degeneration (1 paper, 2022). "To investigate the role of MAT2A in the pathogenesis of disc degeneration, we performed our pilot study." (PMID 35069973, 2022). "In the disc degeneration animal model, decreased MAT2A expression was also found in degenerative NP tissue tissues." (PMID 35069973, 2022). "However, the role of MAT2A in the pathogenesis of disc degeneration and in the apoptosis of NPCs under oxidative stress has never been investigated." (PMID 35069973, 2022). "To confirm that functional inhibition of MAT2A in NP will increase the apoptosis of NPCs and lead to disc degeneration, we injected the inhibitor of MAT2A called cycloleucine (CLEU) and the control substance phosphate buffered saline (PBS) into the caudal intervertebral discs." (PMID 35069973, 2022). "To investigate the function of MAT2A and METTL16 in the apoptosis of NPCs and finally their role in the pathogenesis of disc degeneration, we downregulated the expression of MAT2A in NPCs with small interfering RNA (siRNA) while upregulated the expression of METTL16 in the NPCs with lentivirus." (PMID 35069973, 2022). "Thus, we speculate that oxidative stress aggravates the apoptosis of the NPCs through m6A modification of MAT2A by METTL16 and finally leads to disc degeneration." (PMID 35069973, 2022).
Fanconi anemia (1 paper, 2024). Fanconi anemia (FA) is a hereditary DNA repair disorder characterized by progressive pancytopenia with bone marrow failure, variable congenital malformations and predisposition to develop hematological or solid tumors. "It was reported that MAT2A inhibition regulates Fanconi anemia (FA) DNA repair pathway by the accumulation of DI transcripts." (PMID 39309689, 2024).
hypermethioninemia (1 paper, 2024). "However, although hepatic MAT1A and MAT2A expression is up-regulated at the protein level after MAT2A inhibition, the capacity of the liver of treated animals to metabolize methionine is markedly diminished, which leads to hypermethioninemia and subsequent reduced SAM levels." (PMID 38755480, 2024).